AURKA (aurora kinase A)
Diseases named in the same sentence as AURKA in open-access papers (continued):
Sharing a sentence is not in itself a finding about the gene and the disease.
pancreatic cancer (42 papers, 2009 to 2025). "Among other kinases, Aurora kinase A has been reported to be overexpressed in pancreatic cancer and is also reported to play a role in causing dysplasia in pancreatic ducts." (PMID 37371811, 2023). "The F-box and leucine-rich repeat protein 7 (FBXL7) is a potential tumor-suppressing gene, one that is frequently hypermethylated in pancreatic cancer and where the encoded protein promotes the degradation of AURKA, BIRC5 and c-SRC." (PMID 35887149, 2022). "Overexpression of AURKA was reported in pancreatic cancer, in the early stages of abnormalities in pancreatic ducts and ductal dysplasia in transgenic mouse model for pancreatic cancer, and linked to chromosome instability and centrosome abnormality." (PMID 25987188, 2015). "Targeting AURKA activation using inhibitors like MLN8237 (Alisertib) in pancreatic cancers (PancT4 cell line and Primary cells from tumors) suppresses tumor formation." (PMID 40568758, 2025). "Similar non-specificity in pS194RALA detection using this antibody was previously observed in pancreatic cancer cells upon AURKA inhibition using MLN8237 and siRNA-mediated RALA KD (PANC1 cells)." (PMID 40568758, 2025). "A recent genome-wide CRISPR/Cas9 knockout screen identified that aurora kinase A knockout or inhibition sensitizes pancreatic cancer cell lines to elraglusib." (PMID 39470360, 2024). "AURKA expression is stimulated via a KRAS mutation, and high AURKA expression predicts unfavorable clinical outcomes in patients with pancreatic cancer." (PMID 37568682, 2023). "A growing number of studies have identified AURKA as a key player in different types of cancers, such as gastrointestinal and pancreatic cancers, and it has been proposed as a molecular therapeutic target for tumorigenesis." (PMID 37458462, 2023). "Overexpression of BLM, AURKA and PITX1 has previously been linked with poor survival in breast, lung, bladder and pancreatic cancer." (PMID 32899298, 2020). "AURKA belongs to the aurora kinases family, and its up-regulation in pancreatic cancer is related to the poor overall survival." (PMID 32548103, 2020). "We recently showed that Re-NHC complexes suppress the growth of pancreatic cancer cell lines by blocking the cells in the G2/M phase via a mechanism involving the inhibition of phosphorylation of aurora kinase A." (PMID 33287862, 2020). "In parallel, we investigated the ability of SA16 and IB35 to inhibit Aurora kinase A phosphorylation at the Thr288 site in pancreatic cancer cell lines synchronized with nocodazole (200 ng/mL)." (PMID 31683659, 2019). "We next determined the effect of the dual PDK1/Aurora Kinase A inhibitors on cell growth using a panel of five human pancreatic cancer cell lines displaying distinct genetic complexity, and on one non-malignant human pancreatic duct cell line (hTERT-HPNE)." (PMID 31683659, 2019). "Here, we tested two drugs displaying dual inhibitory activity towards PDK1 and Aurora kinase A in a panel of pancreatic cancer cell lines and in two in vivo models of pancreatic cancer." (PMID 31683659, 2019). "In BxPC3 pancreatic carcinoma cells Aurora kinase-A mediated phosphorylation of TW at S123, T148 and S184 promote increased malignant phenotypes and inhibit TW heterodimerization with E12 and Hand2." (PMID 31540485, 2019). "AURKA depletion inhibits in vivo tumorigenicity, enhances taxane chemosensitivity, and induces apoptosis in pancreatic cancer cells." (PMID 28193222, 2017). "Our discovery of ALDH1A1 as an AURKA substrate provides a novel mechanism by which AURKA promotes chemoresistance and stem cell formation in pancreatic cancer via ALDH1A1 and vice versa." (PMID 28193222, 2017). "We focused on Aurora kinase A (AURKA), as it is overexpressed in a vast majority of pancreatic tumors." (PMID 28193222, 2017). "Several studies have shown that AURKA is frequently amplified in several tumors including breast, leukemia, bladder, ovarian, gastric, esophageal, liver, colorectal, and pancreatic cancers." (PMID 25987188, 2015).
pancreatic cancer (continued). "This signaling loop further underscores the potential therapeutic benefit of targeting AURKA in pancreatic cancer." (PMID 25987188, 2015). "Knockdown of AURKA in pancreatic cancer cells results in cell cycle arrest at G2/M and hence, suppression of cellular proliferation." (PMID 25699241, 2015). "Since AURKA (Aurora-A kinase) plays an important multifunctional role in pancreatic cancer, we further investigated the function and regulation of AURKA in pancreatic cancer cells." (PMID 25912306, 2015). "Aurora kinase A is overexpressed in the majority of pancreatic cancers, which is consistent with the observation that most pancreatic cancers produce constitutively active MAPK." (PMID 25699241, 2015). "Genetic or pharmacological inhibition of AURKA significantly inhibited GSK3β S9 phosphorylation in pancreatic cancer cells, suggesting that GSK3β might indeed act as a downstream target of AURKA in necroptosis." (PMID 39334449, 2024). "Aurora kinase A (AURKA) is a serine/threonine cell cycle kinase that is aberrantly expressed and over-amplified in many cancers, including colorectal, gastric and pancreatic cancers, leading to genetic mutations, morphological changes and promoting carcinogenesis." (PMID 38612711, 2024). "Moreover, Aurora kinase A has been reported as a downstream target in the MAPK1/ERK2 signaling pathway in pancreatic cancer." (PMID 37371811, 2023). "The AURKA selective inhibitor alisertib could induced cell cycle arrest and facilitated autophagic cell death in pancreatic cancer cells." (PMID 30598639, 2018). "Interestingly, TWIST1 and AURKA have very recently been seen to form a feedback loop promoting metastasis and highly aggressive phenotypes in pancreatic carcinoma, and TWIST1 is a marker for EMT in neuroendocrine tumours." (PMID 29757368, 2018). "To examine whether AURKA-mediated regulation of ALDH1A1 was common in other pancreatic cancer cells, we investigated ALDH1A1 subcellular localization in Panc1 cells in the absence or presence of either AURKA shRNA or MLN8237." (PMID 28193222, 2017). "However, future studies are needed to explore whether AURKA-TWIST1 signaling plays a role in EMT paradigm beyond pancreatic cancer." (PMID 39334449, 2024). "have discovered the crucial role of Aurora Kinase A (AURKA)-Twist1 axis in promoting EMT and chemoresistance of pancreatic cancer." (PMID 35651786, 2022). "The model simulations proposed the proteins AURKA, CD44, PAK1, STAT3, and TWIST1 as promising therapeutic targets for pancreatic cancer." (PMID 33578795, 2021). "In order to evaluate the possibility to use dual PDK1/Aurora kinase A inhibitors as potential in vivo therapeutics, we performed a xenograft experiment using HPAF-II human pancreatic cancer cell line." (PMID 31683659, 2019). "We observed similar AURKA-mediated positive regulation of ALDH1A1 in Panc1 cells, suggesting that it is a common mechanism in pancreatic cancer cells." (PMID 28193222, 2017). "AURKA inhibition reduced the levels of N-cadherin, CD44, vimentin, MMP-2, Slug, and Snail, but increased E-cadherin levels in pancreatic cancer cell lines." (PMID 28193222, 2017). "Our mechanistic hypothesis is supported by gene expression data, showing that both AURKA and TCF7L2 are significantly overexpressed in pancreatic tumor tissues in comparison to healthy donors." (PMID 33578795, 2021). "Indeed, AurkA is regulated by KRAS via the MAPK signalling pathway, and, consequently, AurkA is ectopically expressed in pancreatic cancer and KRAS knockdown in PDAC cell lines leads to depletion of AurkA and cilia formation." (PMID 32571902, 2020). "As AURKA overexpression is also associated with enhanced chemoresistance, we hypothesized that AURKA may upregulate ALDH1A1 leading to EMT, CSC phenotypes, and chemoresistance in pancreatic cancer." (PMID 28193222, 2017).
pancreatic cancer (continued). "Thus, targeting AURKA and ALDH1A1 in combination is expected to be highly effective in inhibiting tumorigenesis, chemoresistance, and metastasis in highly lethal pancreatic carcinoma." (PMID 28193222, 2017). "In this study, two novel dual inhibitors targeting PDK1 and Aurora kinase A have been tested in a panel of pancreatic cancer cell lines and compared to non-malignant cells to check the effect of their activity on PI3K and Aurora kinase A pathways, and their potential as anticancer agents." (PMID 31683659, 2019). "While extreme chemoresistance and CSC formation are the defining features of pancreatic cancer, the mechanism by which AURKA may be involved in these processes has not been examined." (PMID 28193222, 2017).
melanoma (39 papers, 2012 to 2025). A malignant, usually aggressive tumor composed of atypical, neoplastic melanocytes. "In particular, AURKA overexpression in melanoma has been associated with gene amplification and copy number gain, although transcription activation and post-transcriptional mechanisms can increase AURKA expression even in the absence of gene amplification." (PMID 37259298, 2023). "In melanoma cells, a mutation in a key AURKA-inactivating phosphatase results in aberrant AURKA activation and its sustained interaction with TPX2." (PMID 34944109, 2021). "Alisertib (ALS), a selective inhibitor of Aurora kinase A (AURKA), has been employed in melanoma treatment." (PMID 40331942, 2025). "CDCA2 can act on SMAD-specific E3 ubiquitin protein ligase 1 and inhibit the degradation of ubiquitin-dependent Aurora kinase A (AURKA) to promote melanoma progression." (PMID 39247594, 2024). "For example, CCL5 (Chemokine (C-C motif) ligand 5) secreted by Aurora kinase A (AURKA) or CDK4/6 inhibitor-induced melanoma senescent cells promotes the recruitment of tumor-infiltrating leukocytes (TILs), enhancing their killing effect on tumor cells." (PMID 37174106, 2023). "In this way, pharmacological inhibition of AURKA by MLN8237 (alisertib) resulted in the reduction of melanoma cell proliferation and induced senescence and apoptosis in cells with BRAF and NRAS mutation, and in vemurafenib (BRAF inhibitor) resistant cells." (PMID 37259298, 2023). "In melanoma, the combination of AURKA inhibitors and MDM2 inhibitors synergistically promoted anti-tumor immune cell infiltration in immunocompetent mice." (PMID 35205315, 2022). "To investigate the defective ATM checkpoint function produced by dysregulated AURKA- PLK1 pathway, we stably over-expressed wild type AURKA in two ATM checkpoint functional melanoma cells lines, A2058 and A375." (PMID 33993200, 2021). "After co-culture with autologous TILs, melanoma cells overexpressing AURKA or AURKB were more resistant to T-cell-mediated cytotoxicity, as evidenced by decreased comboscores." (PMID 33123754, 2021). "Both in that dataset and in an independent dataset of melanoma samples derived from patients treated with anti-PD-1 therapy, AURKA, AURKB, and CDCA8 expression were higher in tumors that did not respond to immunotherapy." (PMID 33123754, 2021). "In an independent, publicly available RNA sequencing dataset of patient-derived melanoma samples, AURKA, AURKB, and CDCA8 showed trends toward increased expression in patients who did not respond to anti-PD-1 therapy (progressive disease)." (PMID 33123754, 2021). "In this study, we investigated the effects of ALS, a potent and selective inhibitor of AURKA, on melanoma cells." (PMID 29291012, 2017). "We investigated the efficacy of Alisertib (ALS), a selective Aurora kinase A (AURKA) inhibitor, in melanoma." (PMID 29291012, 2017). "A concomitant AURKA/BRAF and AURKA/MEK targeting overcame MAPK signaling activation-associated resistance signature in BRAF- and NRAS-mutated melanomas, respectively, and elicited heightened anti-proliferative activity and apoptotic cell death." (PMID 26962685, 2016). "Consistently, in contrast to the observations with BRN2, AURKA inhibition induced p(Ser133)-CREB levels in all the tested melanoma cell lines." (PMID 26962685, 2016). "AURKA expression levels showed highly significant increase with melanoma progression from nevi (n=9) to primary (n=31) and from primary to metastatic (n=52) stage." (PMID 26962685, 2016). "Consistent with earlier observations, abrogation of AURKA function triggered a massive accumulation of melanoma cells in G2/M phase." (PMID 26962685, 2016). "To further understand the role of AURKA in melanoma cell biology, we investigated its requirement in cell viability, utilizing a large panel of melanoma cell lines that encompassed the entire gamut of major melanoma-associated molecular alterations." (PMID 26962685, 2016).
melanoma (continued). "The list comprises of several well-known melanoma-associated-oncogenes including RAF1, AURKA and SRC along with putative novel oncogenes." (PMID 26558755, 2015). "Aurora kinase A (AurkA), one of the key regulators of M phase progression, has been shown to be expressed at high levels in melanoma." (PMID 25074438, 2014). "Aurora kinase A (AurkA) is over-expressed in melanoma and its inhibition has been observed to limit tumor growth, suggesting a potential role in melanoma treatment." (PMID 25074438, 2014). "AurkA inhibition has been shown to limit tumor growth, impair mitosis and induce senescence in melanoma, suggesting a potential role in the treatment of these tumors." (PMID 25074438, 2014). "AurkA inhibitor plus B-RAF inhibitor, AurkA inhibitor plus MEK inhibitor or triple combination had a markedly greater anti-proliferative effect on A375 (BRAFV600E) melanoma cells than single agents." (PMID 25074438, 2014). "To evaluate AURKA as a therapeutic target in melanoma, we targeted AURK in human melanoma tumour implants growing in mice using an AURK inhibitor currently in clinical trials for solid tumours." (PMID 23180582, 2013). "Genes deregulated at the DNA and mRNA level included well-known cancer genes partly already linked to melanoma (RAS genes, PTEN, AURKA, MAPK inhibitors Sprouty/Spred), but also novel candidates like SIPA1 (a Rap1GAP)." (PMID 22535842, 2012). "We investigated the role of AURKA in tumorigenesis in a mouse model of melanoma." (PMID 29291012, 2017). "Aberrant AURKA expression and activity have been demonstrated in several cancers including breast, bladder, colon, ovarian, liver, pancreatic, stomach, and esophageal cancer as well as melanoma." (PMID 29291012, 2017). "Surprisingly, AURKA inhibition induced MITF expression in all tested melanoma cell lines." (PMID 26962685, 2016). "To conclude, this study, whilst potentially bearing fundamental implications for the application of AURKA inhibitors as melanoma therapeutics, describes a common framework for future target discovery, whereby the functional significance of cooperating oncogenic events is addressed at the outset." (PMID 26962685, 2016). "In contrast, a cell cycle-dependent regulation, as previously reported for a functionally related Polo-Like Kinase 141 might be a more conceivable mechanism of elevated AURKA expression levels with melanoma progression." (PMID 26962685, 2016). "MAPK cascade induction in human melanoma cells could therefore jeopardize the success of AURKA interference approaches." (PMID 26962685, 2016). "Combined BRAF/AurkA inhibition might offer a therapeutic alternative to BRAF/MEK inhibition for BRAF-mutated melanomas, while a combination of MEK/AurkA inhibitors could represent a possible option for patients without BRAF mutations." (PMID 26322273, 2015). "Inhibition of AurkA protein, which seems to be expressed at high levels in melanoma, has been shown to limit tumor growth, impair mitosis, and induce senescence in melanoma, suggesting a potential role as therapy target." (PMID 26322273, 2015). "Although a recent study reported overexpression of AURKA and AURKB in human melanoma at the tissue level, it is possible that the elevated expression of AURKA and AURKB was due to the high proliferative capacity of cancer cells, since AURKs are expressed largely during cell division." (PMID 23180582, 2013). "Furthermore, all tested melanoma lines exhibited apoptotic cell death upon AURKA inhibition." (PMID 26962685, 2016).